BCL9 (BCL9 transcription coactivator)
Diseases named in the same sentence as BCL9 in open-access papers (continued):
Sharing a sentence is not in itself a finding about the gene and the disease.
gastric cancer (8 papers, 2017 to 2024). A primary or metastatic malignant neoplasm involving the stomach. "Taken together, miR-30a acts as a tumor suppressor by double-targeting COX-2 and BCL9, and significantly affects the development of H. pylori-induced gastric cancer, shedding new light on the mechanisms underlying H. pylori-associated gastric cancer." (PMID 28769030, 2017). "The study has indicated that miR-22-3p can inactivate the Wnt/β-catenin to inhibit the progression of via gastric cancer directly targeting BCL9." (PMID 35340229, 2022). "Here, we further examined the expression of BCL9 in sorted ITGB+/- gastric cancer cells SGC-7901 and BGC-823(cultured in 3D collagen gel or not)." (PMID 34319913, 2021). "Next, we further investigated the effect of miR-30a-5p on the BCL9-TCF/LEF signaling pathway in H. pylori-infected gastric cancer MKN45 cells." (PMID 28769030, 2017). "Taken together, our results indicated that, the function of miR-30a in the development of H. pylori-induced gastric cancer was associated closely with the regulation of COX-2, BCL9, VEGF and CD34." (PMID 28769030, 2017). "All these results suggested that, miR-30a was associated closely with the development of H. pylori-induced gastric cancer, and regulated the genes closely associated with tumor development such as COX-2, BCL9, nuclear β-catenin, VEGF and CD34." (PMID 28769030, 2017). "However, the detailed mechanism of miR-30a-5p targeting BCL9 to regulate the downstream gene expression or involved signaling pathways in H. pylori-infected gastric cancer is unclear." (PMID 28769030, 2017). "MiR-30a is crucial for regulation of growth and migration of Heliobacter pylori–infected gastric cancer via targeting COX-2 and B cell CLL/lymphoma 9 (BCL 9)." (PMID 31379585, 2019). "Using IHC staining, we detected the protein expression levels of COX-2, BCL9, VEGF, and CD34 in tissue samples from patients with H. pylori gastritis, H. pylori-related gastric cancer and healthy controls." (PMID 28769030, 2017). "Our present study found that, miR-30a is crucial for regulating the growth and migration of H. pylori infected gastric cancer in vitro by targeting COX-2 and BCL9." (PMID 28769030, 2017). "Since Wnt/β-catenin served as the downstream signal of BCL9, we supposed that ITGB1 might upregulate BCL9L to mediate the activation of pro-survival β-catenin signals in gastric cancer." (PMID 34319913, 2021). "Previous reports have implicated the role of BCL9 in tumor development and our study further disclosed the pro-tumor effects of BCL9 paralog BCL9L, which could promote the β-catenin signals activation in gastric cancer." (PMID 34319913, 2021). "In addition, the IHC staining and real-time PCR results of COX-2, BCL9, VEGF, CD34, miR-30a-5p and miR-30a-3p in human tissue samples from patients with H. pylori gastritis, H. pylori-related gastric cancer and healthy controls were also in agreement with those findings in vitro and in vivo." (PMID 28769030, 2017).
prostate carcinoma (6 papers, 2011 to 2023). A carcinoma that arises from epithelial cells of the prostate gland. "Genetic analysis of large prostate cancer datasets has revealed that several co-activators of β-catenin-mediated transcriptional activity are amplified in prostate cancer, such as BCL9 and PYGO2." (PMID 35204808, 2022). "The transcription factor BCL9 is over-expressed in a number of human malignancies, including prostate cancer, to promote tumor growth by upregulating the transcription of Wnt target genes." (PMID 35204808, 2022). "BCL9 possesses hypoxia-responsive elements in its promoter region, and hypoxia and HIF1α induce BCL9 expression in liver, colon, and prostate cancer cells." (PMID 35027586, 2022). "BCL9 possesses hypoxia-response elements in its promoter region, and hypoxia and HIF1α induce BCL9 expression in liver, colon, and prostate cancer cells." (PMID 35027586, 2022). "The list of up and downregulated genes in VEGFA165 tumours include known genes involved in neoplasia (e.g. S100A8 involved in leukaemia; S100A9 in prostate carcinoma; BCL9, CCND1 and CTNNB1)." (PMID 22045186, 2011). "Moreover, miR-30c and BCL9 expression inversely correlate with prostate cancer." (PMID 35204808, 2022).
leukemia (5 papers, 2011 to 2022). A malignant (clonal) hematologic disorder, involving hematopoietic stem cells and characterized by the presence of primitive or atypical myeloid or lymphoid cells in the bone marrow and the blood. "BCL9 transcription coactivator has been reported to mediate pro-survival signaling pathways activation and correlated with lymphoma and leukemia development." (PMID 34319913, 2021). "BCL9 (B-cell CLL/lymphoma 9) and its homologue BCL9L (B-cell CLL/lymphoma 9-like, BCL9-2, DLNB11) have previously been shown to be associated with the formation of leukemia and other human malignancies." (PMID 27713160, 2016). "This demonstrated sensitivity to the HDAC inhibitor panobinostat (but little sensitivity to BCL9 inhibitors), suggesting HDAC inhibition as a therapeutic option in this high-risk form of leukaemia." (PMID 27824051, 2016).
triple-negative breast carcinoma (5 papers, 2021 to 2025). An invasive breast carcinoma which is negative for expression of estrogen receptor (ER), progesterone receptor (PR), and human epidermal growth factor receptor 2 (HER2). "The expression of BCL9/BCL9L negatively related to the infiltration of CD8+ T cells in triple negative breast cancer, and BCL9/BCL9L inhibited the infiltration of CD8+ T cells in the tumor microenvironment." (PMID 34579753, 2021). "Hypomethylation within this gene in CLL patients with SF3B1 mutation has been previously reported and it has been recently shown that BCL9 and BCL9L promote tumorigenicity in a triple negative breast cancer mouse model through immune-dependent (TGF-β) and immune-independent (Wnt) pathways." (PMID 34502260, 2021).
B-cell acute lymphoblastic leukemia (4 papers, 2019 to 2024). A neoplasm of lymphoblasts committed to the B-cell lineage, typically composed of small to medium-sized blast cells. "BCL9 is a specific gene functionally related to B-cell acute lymphoblastic leukemia and participates in Wnt/β-catenin and GPCR signaling pathways." (PMID 31480430, 2019).
intestinal tumor (4 papers, 2016 to 2023). "BCL9L (B-cell CLL/lymphoma 9 like) protein shares a conserved domain with BCL9, which is related to intestinal tumor progression." (PMID 30670769, 2019). "In contrast, Pygo2, similar to Bcl9/Bcl9-2, may drive intestinal tumor formation by increasing aberrant Wnt signaling in vivo." (PMID 27811361, 2016).
melanoma (4 papers, 2018 to 2024). A malignant, usually aggressive tumor composed of atypical, neoplastic melanocytes. "Our expression analysis showed downregulated expression of BCL9 in melanoma cells transfected with miR-30c-1* or miR-193b, while BCL9 expression was enhanced in miR-576-5p transfected cells." (PMID 30197759, 2018). "The expression levels of the identified target genes encoding CTGF, THBS1, STMN1, BCL9, RAC1 and MCL1 allowed discrimination between phenotypic groups of melanoma cell lines with high or low-invasive capacity, respectively." (PMID 30197759, 2018). "This study reveals opposed effects of miR-193b / miR-30c-1* and miR-576-5p, respectively, on melanoma cell invasion and on expression of BCL9 and MCL1, possibly accounting for the contrasting invasive phenotypes observed in A375 cells transfected with these miRNAs." (PMID 30197759, 2018).
B-cell lymphoma (3 papers, 2016 to 2025). "Because numerous genes located on chromosome 1q21 are linked to B-cell lymphoma, including BCL9, MCL1, and IRTA1, a gene on chromosome 1q21 in this patient might be dysregulated due to the IGL translocation." (PMID 40729218, 2025).
bladder cancer (3 papers, 2014 to 2026). "Pharmacological inhibition of the β-catenin/BCL9(L) complex using ZW4864 suppresses a subset of Wnt/β-catenin targets in bladder cancer cells, indicating the inhibition of canonical Wnt signaling." (PMID 42316797, 2026). "In this study, we investigated the contribution of BCL9(L) (coactivators of β-catenin) to bladder cancer progression and evaluated the therapeutic potential of disrupting the β-catenin/BCL9(L) complex." (PMID 42316797, 2026). "We demonstrate that BCL9L exerts oncogenic effects on the proliferation and invasion of bladder cancer cells and the knockdown of BCL9 also reduced the proliferation, migration, and invasion of bladder cancer cells, suggesting similar oncogenic roles." (PMID 42316797, 2026).
invasive breast carcinoma (3 papers, 2015 to 2023). A carcinoma that infiltrates the breast parenchyma. "Interestingly, analysis of TCGA data (provisional TCGA; 959 cases) showed that 26 % of invasive breast cancers contain BCL9 gene alterations." (PMID 26384318, 2015). "BCL9 is a molecular driver of DCIS invasive progression and may predispose to the development of basal like invasive breast cancers." (PMID 26384318, 2015).
major depressive disorder (3 papers, 2013 to 2023). An episode of depression lasting two or more weeks without an intervening episode of mania. "The BCL9 gene encoding the protein we found was associated with major depressive disorder." (PMID 37894929, 2023).
osteosarcoma (3 papers, 2020 to 2023). A usually aggressive malignant bone-forming mesenchymal neoplasm, predominantly affecting adolescents and young adults. "SNHG16 expression is up-regulated in osteosarcoma and promotes the occurrence and development of osteosarcoma through the SNHG16/miR-1301/BCL9 axis." (PMID 35070996, 2021).
ovarian carcinoma (3 papers, 2019 to 2022). A malignant neoplasm originating from the surface ovarian epithelium. "High BCL9 expression was associated with 5-year PFS and 5-year OS in ovarian cancer patients, suggesting that BCL9 expression and may serve as an independent biomarker for predicting survival and prognosis in ovarian cancer patients." (PMID 31827404, 2019). "The level of BCL9 expression was correlated with the 5-year progression-free survival rate and overall survival rate in ovarian cancer patients and independently predicted the risk of ovarian cancer recurrence." (PMID 31827404, 2019). "The results showed that the rate of the early apoptosis of ovarian cancer cells significantly increased after inhibiting the expression of BCL9." (PMID 31827404, 2019). "To analyze the effect of BCL9 expression on the invasion and migration of ovarian cancer cells, we decreased BCL9 expression and detected changes in related proteins." (PMID 31827404, 2019). "The results of both the scratch test and transwell test showed that ovarian cancer cells with low BCL9 expression had lower migration and invasion ability than the control group." (PMID 31827404, 2019). "Low BCL9 expression can promote cell apoptosis, inhibit the proliferation, invasion, and migration of ovarian cancer cells." (PMID 31827404, 2019). "The MTT results showed that when the expression of BCL9 decreased, the viability of ovarian cancer cells in both groups significantly decreased." (PMID 31827404, 2019). "Based on the literature and bioinformatics analyses, BCL9 appears to promote the development of ovarian cancer by regulating the Wnt signaling pathway." (PMID 31827404, 2019). "This indicates that the decrease in BCL9 expression inhibited ovarian cancer cell proliferation by promoting the apoptosis of ovarian cancer cells by increasing the BAX/BCL2 expression ratio." (PMID 31827404, 2019). "We used Western blot to detect BCL9 expression in CaoV3, Ovcar3, Skov3, and ES-2 ovarian cancer cell lines." (PMID 31827404, 2019). "BCL9 is overexpressed in epithelial ovarian tumors, resulting in a poor prognosis for ovarian cancer patients." (PMID 31827404, 2019). "BCL9 promotes the occurrence and development of ovarian cancer." (PMID 31827404, 2019). "Therefore, the present study explored the expression of BCL9 in human ovarian epithelial tumors and its relationship to clinicopathological parameters and changes in the malignant biological behavior of human ovarian cancer cells." (PMID 31827404, 2019). "Low BCL9 expression can promote ovarian cancer cell apoptosis, inhibit proliferation and migration." (PMID 31827404, 2019). "In the present study, we detected high BCL9 expression in ovarian cancer tissues." (PMID 31827404, 2019). "Both the univariate and multivariate regression analyses indicated that FIGO stage and BCL9 expression were significantly associated with PFS and OS, suggesting that they can be used as biomarkers to independently predict prognosis in ovarian cancer patients." (PMID 31827404, 2019). "Although the precise mechanism of action remains to be determined, small-molecule anti-tumor drugs that target the β-catenin/BCL9 interface may be promising for the treatment of ovarian cancer." (PMID 31827404, 2019). "In addition to miR-30-5p, miR-1301, miR-30a, miR-218, and miR-30c also downregulate the expression of BCL9 in different cancer tissues; among these, miR-30c-2 worked in ovarian cancer." (PMID 31827404, 2019). "Furthermore, correlation analysis between 182 DEGs and MEX3A was applied using TCGA ovarian cancer data to obtain 7 DEGs (CSNKE1, OBSL1, DNASE1, ZNF711, TIMELESS, SAMD11, and BCL9) that were positively associated with MEX3A expression (Spearman’s correlation≥0.3)." (PMID 35715407, 2022). "Therefore, BCL9 appears to affect cell proliferation by regulating the Wnt signaling pathway and other tumor-related signaling pathways to promote the occurrence and development of ovarian cancer." (PMID 31827404, 2019).
ovarian carcinoma (continued). "Therefore, we speculate that BCL9 affects the proliferative capacity of ovarian cancer cells by promoting the apoptosis of ovarian cancer cells, thus promoting the development of ovarian cancer." (PMID 31827404, 2019). "To investigate the effect of BCL9 on the proliferation and apoptosis of ovarian cancer cell lines in vitro, we used the MTT assay to detect changes in the proliferation of ovarian cancer cells after decreasing BCL9 expression." (PMID 31827404, 2019). "We then performed Cox regression analysis to assess the relationship between the level of BCL9 expression, FIGO stage, lymph node metastasis, and survival in patients with ovarian cancer." (PMID 31827404, 2019). "In conclusion, BCL9 is highly expressed in EOC tissues and may be an independent biomarker for predicting prognosis in ovarian cancer patients." (PMID 31827404, 2019). "Thus, in this research, we aimed to investigate the expression and clinical significance of BCL9 in EOC tissues and its effect on the malignant biological behavior of human ovarian cancer cells." (PMID 31827404, 2019). "Low BCL9 expression also downregulated the expression of MMP2 and MMP9 in ES-2 cells, suggesting that BCL9 might dissolve the extracellular matrix of ovarian cancer cells by promoting the expression of MMP2 and MMP9, further promoting the invasion and metastasis of ovarian cancer cells." (PMID 31827404, 2019). "We decreased BCL9 expression in the ovarian CaoV3 serous cancer cell line and ovarian ES-2 clear cancer cell line, which inhibited BCL2 expression and increased the BAX/BCL2 expression ratio, promoted cell apoptosis, and inhibited the proliferation of ovarian cancer cells." (PMID 31827404, 2019). "The expression and role of BCL9 in epithelial ovarian cancer (EOC) have not been studied." (PMID 31827404, 2019). "However, this was not applicable to the CaoV3, which suggested that BCL9 played different degree of role in different cell lines of ovarian cancer." (PMID 31827404, 2019).
adenocarcinoma of the colon (2 papers, 2021 to 2022). "Moreover, a high expression of BCL9 in SW480, a primary human adenocarcinoma of the colon, is accompanied with a high expression of TCF136." (PMID 35027586, 2022).
adenoma (2 papers, 2019). A neoplasm arising from the epithelium. "Loss-of-Bcl9 synergises with loss-of-Pygo to shift gene expression within Apc-mutant adenomas from stem cell-like to differentiation along Notch-regulated secretory lineages." (PMID 30760710, 2019). "An important corollary is that Bcl9 loss strongly synergises with Pygo loss in shifting the adenoma gene expression programme towards that of normal crypts, and argues against an epistatic relationship between the two enhanceosome factors." (PMID 30760710, 2019). "Thus, loss of Pygo or Bcl9 promotes secretory cell metaplasia, apparently at the expense of stem cell-like fates, given the downregulation of Lgr5 and stem cell signature genes in these adenomas." (PMID 30760710, 2019). "To test this apparent epistasis between Bcl9 and Pygo, we determined the RNA profiles in adenomas excised from ApcMinDKO and QKO small intestines (pooled from 2–3 RNA extractions)." (PMID 30760710, 2019). "In contrast, Bcl9/B9l DKO adenoma cells showed very little nucleocytoplasmic β-catenin, which explains the low levels of Wnt target gene expression in these Bcl9-deleted adenomas." (PMID 30760710, 2019). "Immunohistochemistry (IHC) revealed 2 × 3 more lysozyme-positive cells in DKO adenoma vs ApcMin control sections, confirming that the former contain more Paneth cells than adenomas with functional Bcl9 or Pygo." (PMID 30760710, 2019). "This striking change in size distribution from large to minute adenomas indicates that Bcl9 is required for tumour growth." (PMID 30760710, 2019). "By contrast, there were far fewer large adenomas (>1 mm) in Bcl9-deleted ApcMin intestines, although these were embedded within a lawn of tiny adenomas (< 1 mm)." (PMID 30760710, 2019). "We thus examined the subcellular distribution of β-catenin in Bcl9-deleted ApcMin adenomas by immunofluorescence (IF)." (PMID 30760710, 2019). "Thus, simultaneous deletion of Bcl9 and Pygo shifts the transcription programme of ApcMin adenomas from stem cell-like towards normal crypts." (PMID 30760710, 2019). "This redistribution of β-catenin from the nucleus to the cell surface owing to Bcl9 loss was not detectable in Pygo-deleted ApcMin adenomas, likely because β-catenin remains associated with nuclear Bcl9 in this case." (PMID 30760710, 2019). "Strikingly, the Bcl9-deleted Apc1322T intestines showed no adenomas whatsoever at 77 days, and about half of these mice remained disease-free beyond ~450 days." (PMID 30760710, 2019). "To test this, and to address whether Bcl9 is epistatic over Pygo at the level of transcription, we conducted systematic Pearson’s correlations of the significant changes between QKO and control adenomas across all five cohorts." (PMID 30760710, 2019).
adrenal cortical tumor (2 papers, 2019 to 2023). "Only 5.8% of the ACA cohort revealed more than a double increase of BCL9 expression levels, while 40 percents of the ACA tissues displayed a double expression upregulation, indicating that upregulation of BCL9 expression in adrenocortical carcinoma is correlated to the malignant characters." (PMID 38269250, 2023).
autism spectrum disorder (2 papers, 2012 to 2018). A spectrum of developmental disorders that includes autism, and Asperger syndrome. "Microdeletion and microduplication copy number variations are found in patients with autism spectrum disorder and in a number of cases they include genes that are involved in the canonical Wnt signaling pathway (for example, FZD9, BCL9 or CDH8)." (PMID 23083465, 2012).
bilharziasis (2 papers, 2022 to 2023). "Our finding indicated that CNV of BCL9 did not affect HCC development in our patient cohort, but it was found that gender, bilharziasis, performance status, child score class, child grade, focal lesion size, portal vein, and ascites have correlated with HCC development and prognosis." (PMID 34978646, 2022).
breast tumor (2 papers, 2014 to 2026). "We found, that primary cell cultures of BCL9-2 breast tumors responded to tamoxifen treatment." (PMID 25149534, 2014).